BRAF (B-Raf proto-oncogene, serine/threonine kinase)
Diseases named in the same sentence as BRAF in open-access papers (continued):
Sharing a sentence is not in itself a finding about the gene and the disease.
melanoma (continued). "Twenty-one melanoma cell lines containing mutations in the BRAF gene were evaluated to determine sensitivity to SCH772984 (ERKi)." (PMID 25142146, 2014). "Although dacarbazine has been the standard first-line chemotherapy for decades, new therapies such as molecular-targeting agents against BRAF-mutated melanoma or the anti-CTLA4 monoclonal antibody ipilimumab have improved the survival rate." (PMID 25422890, 2014). "In general, BRAF mutated protein is present in all tumor cells indicating that this genetic aberration is a common clonal event in melanoma." (PMID 25526463, 2014). "Multiple genetic parameters have been associated with response to chemotherapy, but despite their high frequency in melanoma nothing is known about the impact of BRAF or NRAS mutations on the response to chemotherapeutic agents." (PMID 24941944, 2014). "Conversely, an association between a mixed cell population and BRAF wild-type phenotype was observed, which reached statistical significance among distant melanomas." (PMID 25526463, 2014). "We used the BRAF inhibitor vemurafenib to treat a patient presenting a rare p.V600_K601delinsD-mutated melanoma." (PMID 25265970, 2014). "The BRAF-activating mutations have been reported in various type of cancer: melanoma (70% of cases), thyroid (30-70%), ovarian (15-30%) and colorectal cancer (5-10%)." (PMID 25267307, 2014). "The most common melanoma mutation in BRAF exon 15, the activating mutation V600E, leads to response rates of more than 50% of all patients treated with the specific TKI Vemurafenib." (PMID 24879454, 2014). "To address this possibility we compared expression levels of the key kinases and two major negative regulators of the pathway, SPROUTY2 and RKIP, in the GHM vs. human melanoma cell lines with activated ERK1/2 due to oncogenic BRAF or NRAS mutations." (PMID 25413220, 2014). "The aim of the present study was to investigate the prognostic impact of BRAF-V600 tumor mutations in melanoma patients receiving first-line treatment with dacarbazine or temozolomide during the years 2000–2010, before availability of BRAF inhibitors." (PMID 24586605, 2014). "Given its specificity for ERK and the potential for ERK inhibition to inhibit both MAPK and PI3K/AKT pathways, we evaluated the susceptibility of wild-type, mutant BRAF- or NRAS-melanoma, and BRAF-mutant melanoma with acquired BRAFi resistance." (PMID 25142146, 2014). "Although BRAF inhibitors extend survival and improve the quality of life in patients with BRAF V600E-mutated melanoma, variable responses to BRAF inhibitors have been described in different tumor types." (PMID 24725538, 2014). "Frequency rates of BRAF mutations were quite identical across the different types of MPM lesions (first vs. second vs. subsequent melanoma)." (PMID 24885594, 2014). "Authors randomly assigned 495 patients with previously untreated unresectable locally advanced or metastatic BRAF V600 mutation-positive melanoma to receive vemurafenib and cobimetinib (combination group) or vemurafenib and placebo (control group)." (PMID 25374620, 2014). "Slow cycling cells have recently been associated with BRAF inhibitor-resistance and melanoma invasiveness." (PMID 25051363, 2014). "Mutations in BRAF and NRAS (~20% of melanomas of the same origin/location as BRAF-mutated melanomas) are almost always mutually exclusive." (PMID 24743024, 2014). "Treatment options are: chemotherapy with dacarbazine, monoclonal antibody anti- cytotoxic T-lymphocytes-associates antigen 4 (CTLA-4) ipililumab and vemurafenib for melanomas carrying BRAF V600E mutation." (PMID 28548075, 2014). "Surprisingly, patients harboring non-V600E BRAF mutations revealed an objective clinical response similar to V600E melanoma patients." (PMID 24591764, 2014). "About one third (40/122; 32.8%) of subsequent melanomas presented a discrepant pattern of BRAF mutations as compared to incident primary tumors." (PMID 24885594, 2014).
melanoma (continued). "The present study has expanded the detailed molecular analysis of clinical stage III melanoma by the characterization of BRAF and NRAS mutations in a homogeneous group of patients with regional nodal macrometastases." (PMID 24959217, 2014). "The finding that 40 to 60% of malignant melanomas are mutated in BRAF paved the way for searching for specific small molecule inhibitors." (PMID 25557167, 2014). "Notwithstanding the significant discoveries in the genetic aspects of melanoma research in the last two decades, e.g. BRAF activating mutations and other genetic alterations, the melanoma epigenome remains poorly understood." (PMID 25237911, 2014). "Malme-3 and Malme-3M cells were collected from the same patient and represent normal epithelial-bearing wild-type BRAF and melanoma cells with the V600E BRAF mutation, respectively." (PMID 25275294, 2014). "We examined the activity of CH5126766/RO5126766 in a panel of malignant tumor cell lines including melanoma with a BRAF or NRAS mutation." (PMID 25422890, 2014). "We present the first survival analysis of melanoma patients focusing on the BRAF mutational status of an unselected real life cohort." (PMID 24586605, 2014). "Eight patients were tested for BRAF mutations in codons 595-600 of exon 15 of the BRAF oncogene; 1 patient tested positive for the BRAF V600E mutation (melanoma)." (PMID 25587555, 2014). "The T1799A mutation of the BRAF gene, which was originally found in >50% of malignant melanomas and a smaller percentage of colon cancers, occurs in 50–83% of PTC in Korea, where iodine consumption is very high." (PMID 25329702, 2014). "The discovery of a highly recurrent mutant allele of the gene encoding the RAF-family kinase BRAF in human melanoma through cancer genome resequencing has set the stage for revolutionary new treatment strategies for this challenging disease." (PMID 25031620, 2014). "As known, about 50% of melanomas harbour mutations in the BRAF gene, mainly at codon 600 (BRAF V600), resulting in constitutive activation of the MAPK pathway." (PMID 25437182, 2014). "Vemurafenib, a BRAF inhibitor recently approved by the United States Food and Drug Administration for therapy of melanoma with a V600E mutation, was initiated as an off-label use." (PMID 24725538, 2014). "Overexpression of MITF desensitizes BRAF-mutated melanoma cells to BRAFi, but MITF expression can be impaired following treatment with histone deacetylase inhibitors (HDACi), suggesting the potential benefit of a combination strategy with MAPK inhibitors." (PMID 25344914, 2014). "Among the BRAF mutations observed in melanoma, over 90% are in codon 600, and among these, over 90% are a single nucleotide mutation resulting in substitution of glutamic acid for valine (BRAFV600E: nucleotide 1799 T>A; codon GTG>GAG)." (PMID 25361007, 2014). "Further investigation of resistance mechanisms has suggested that BRAF-mutated melanoma cells can maintain MAPK signaling through RAF-independent activation of MEK, a kinase downstream of RAF in the MAPK cascade." (PMID 25610709, 2014). "The combined effect of DCA and the BRAF inhibitor vemurafenib was investigated in BRAFV600E -mutated melanoma cell lines." (PMID 25182332, 2014). "Although melanoma is the most aggressive skin cancer, recent advances in BRAF and/or MEK inhibitors against BRAF-mutated melanoma have improved survival rates." (PMID 25422890, 2014). "A375, a melanoma cell line featuring constitutive activation of the MAPK pathway due to the activating BRAF mutation V600E, was treated with three pharmacological kinase inhibitors." (PMID 25188314, 2014). "Analyses of 44 patients, treated in this study, with advanced BRAF V600 mutated melanoma that are either vemurafenib naïve or previously progressed on vemurafenib were presented." (PMID 24693430, 2014).
melanoma (continued). "Vemurafenib, the first drug specifically targeting BRAF-mutated melanoma, has become increasingly popular, and others have been developed in the wake of its success." (PMID 25198196, 2014). "Although the roles of the BRAF V600E mutation in melanoma have been widely studied, several other mutations identified in the BRAF gene are known to cause relatively lower kinase activity." (PMID 25422890, 2014). "In melanoma, V600E BRAF mutation results in constitutive activation of MAPK signaling and aberrant proliferation." (PMID 28548075, 2014). "Vemurafenib, a selective inhibitor of genetically activated BRAF, is registered for unresectable stage III and stage IV melanomas harboring a BRAF mutation." (PMID 25515496, 2014). "A recently published meta-analysis of four studies including mainly metastatic patients reported an 1.7-fold increased risk of dying from melanoma for BRAF mutant patients relative to wild-type patients." (PMID 24475086, 2014). "BRAF inhibitors, such as vemurafenib, have demonstrated improvements in the overall survival of patients with advanced melanoma that harbour a BRAF V600 mutation." (PMID 24693430, 2014). "In melanoma, deregulation of survival pathways as a consequence of BRAF mutation is a frequent event." (PMID 24980831, 2014). "As expected, this list included well documented frequent oncogenic drivers of melanoma, including hotspot mutations in BRAF, NRAS, RAC1, PPP6C, TRRAP, MAP3K5 and BCL2L12." (PMID 24913145, 2014). "As expected, the activity of the BRAF inhibitor, vemurafenib is highly selectively for the BRAF-V600E mutated cell lines, which include most of the melanoma and 2 of the colon cell lines." (PMID 25032700, 2014). "In a later study, microarray data validated by real-time PCR indicated upregulation of Spry2 in melanoma cell lines with mutations in BRAF and NRAS." (PMID 24744103, 2014). "BRAF mutated melanoma cells were more sensitive to fisetin treatment, and this was associated with a decrease in the phosphorylation of MEK1/2 and ERK1/2." (PMID 24466036, 2014). "BRAF V600E mutation are predictive of response to BRAF inhibitors in melanoma and have been reported to predict response in other BRAF-positive malignancies such as hairy cell leukemia, histiocytosis, and thyroid cancer, but not in colorectal cancer." (PMID 25593991, 2014). "In human patients with melanomas that carry BRAF mutation the small molecule BRAF inhibitor vemurafenib (Zorafenib) has shown significant activity with response rates of approximately 50%." (PMID 25022346, 2014). "About one third of patients presented a discrepant pattern of BRAF mutations between incident and subsequent primary melanomas (overall, 40/122; 32.8%)." (PMID 24885594, 2014). "Activation of AKT3 in response to BRAF inhibitor PLX4720 or BRAF siRNA was implicated in the resistance of primary three-dimensional cultures of melanoma cells to BRAFV600E inhibitors." (PMID 24743024, 2014). "First, the oncogenic BRAF mutation contributes to immune escape in melanoma tumors by transcriptional repression of MITF and low MDA expression." (PMID 29250602, 2014). "PPP6C is a serine-threonine phosphatase, mutated in 12% of sun-exposed melanomas exclusively with BRAF or NRAS mutations." (PMID 24743024, 2014). "In this study we provide for the first time both in vitro and in vivo evidence that PDGFRα up-regulation causes BRAF-I resistance of BRAF(V600E) melanoma cells." (PMID 24732172, 2014). "BRAF mutations in melanoma), standards exist that outline treatments for individuals harboring aberrations in the biomarker; however for the vast majority of genomic abnormalities, few guidelines exist." (PMID 25593991, 2014).
melanoma (continued). "The most commonly observed oncogenic events in melanomas are activating mutations in the BRAF and NRAS proto-oncogenes, which occur in 70% of cases." (PMID 24550252, 2014). "The impact of BRAF tumor mutations on the natural course of disease of melanoma patients is controversial." (PMID 24586605, 2014). "A375 is a human-derived melanoma cell line harboring a BRAF mutation due to the substitution of valine for glutamic acid at codon 600, termed V600E resulting in constitutive activation, aggressive proliferation, and high BCL-2 expression." (PMID 24832107, 2014). "In a landmark phase 3 study by Chapman and colleagues, vemurafenib monotherapy showed an overall survival advantage when compared to dacarbazine in treatment-naïve patients with advanced BRAF V600E mutated melanoma." (PMID 24693430, 2014). "A markedly higher rate of either BRAF mutations (59%) or CyclinD1 (38%) or cKIT (13%) amplifications was previously observed in 32 melanoma cell lines as controls by our group (and unpublished data)." (PMID 24885594, 2014). "Loss of neurofibromin expression and NF1 loss-of-function mutations have been reported in melanomas from patients with de novo as well as acquired resistance to BRAF inhibitors." (PMID 25026295, 2014). "Over 50% of all melanoma patients are non-BRAF mutated, with NRAS-mutant and double wild-type comprising 15-20% and 40% of melanoma patients, respectively." (PMID 25142146, 2014). "The data generated for BRAF V600E mutations in melanoma samples also showed concordance in 152/156 (97%) of samples with ARMS or Sanger sequencing demonstrating the accuracy of the MALDI-TOF MS method in BRAF V600E mutations." (PMID 24956168, 2014). "Reliance on glycolysis is a characteristic of malignancy, yet the development of resistance to BRAF inhibitors in melanoma is associated with gain of mitochondrial function." (PMID 25587028, 2014). "Selective BRAF inhibitors such as vemurafenib and dabrafenib are currently approved for the treatment of advanced melanoma patients with BRAF mutation." (PMID 25501056, 2014). "BRAF plays an important role in regulating the mitogen-activated protein kinase (MAPK) signaling cascade in melanoma with activating mutations in the serine/threonine kinase BRAF occurring in 60–70% of malignant melanomas." (PMID 24466036, 2014). "About 50% of melanomas harbor an activating mutation in BRAF, the most common being BRAFV600E, which renders the kinase constitutively active." (PMID 25344914, 2014). "In vivo, MEK inhibitors are effective in NRAS-mutated melanoma, though therapeutic activity is modest compared to BRAFi in BRAF mutant melanoma." (PMID 25142146, 2014). "Collectively, the efficacy of vemurafenib beyond melanoma, for example in Erdheim-Chester Disease and our data argue for ongoing exploration of the therapeutic value of BRAF mutations in LCH." (PMID 24938183, 2014). "BRAF is the most frequently mutated gene in the RAF family, and the BRAF mutation has been reported in 61% of melanoma, 53% of papillary thyroid cancer and 11.5% of colorectal cancer patients." (PMID 25120700, 2014). "In mice injected with BRAF/NF1-mutated melanoma cells, there was resistance to vemurafenib, a BRAF inhibitor." (PMID 25026295, 2014). "Other BRAF mutations do occur, but at much lower rates.Dabrafenib is a kinase inhibitor that inhibits BRAF V600E mutation–positive melanoma." (PMID 25089220, 2014). "Targeted therapies have significantly altered the landscape of oncology, for instance BRAF inhibitors in patients with BRAF-mutated melanoma and ALK inhibitors in patients with ALK-rearranged lung cancer." (PMID 25126591, 2014). "For instance, in a phase 3 clinical trial, melanoma patients with BRAF V600E-mutated melanoma had higher clinical response rates to treatment with the BRAF inhibitor, vemurafenib, than the chemotherapy, dacarbazine." (PMID 25593991, 2014).
melanoma (continued). "Approximately half of all melanoma tumors harbor activating mutations in BRAF, with BRAFV600E and BRAFV600K representing approximately 70–90% and 10–30% of mutations, respectively." (PMID 24733413, 2014). "The P-ERK1/2 levels were comparable to those seen in human melanoma cell lines with oncogenic BRAF or NRAS mutations, in contrast to a cell line with wild-type BRAF and NRAS." (PMID 25413220, 2014). "The selective BRAF inhibitor vemurafenib has demonstrated significant clinical benefits in patients with melanomas harboring the most common mutations (V600E, V600K and V600R)." (PMID 25265970, 2014). "This phase III clinical trial demonstrated that vemurafenib produced improved rates of overall and progression-free survival in patients with previously untreated melanoma with BRAF V600E mutation." (PMID 24455362, 2013). "The health authorities of France (a country with 62 million inhabitants) have set up a network for the detection of somatic mutations in cancers, including BRAF p.V600 mutations in melanomas." (PMID 24119386, 2013). "In a recent phase I trial, ipilimumab was combined with the BRAF inhibitor vemurafenib in melanoma patients with the V600E BRAF mutation." (PMID 24348481, 2013). "Molecular biological studies about melanoma show BRAF mutation is one of the most frequent findings in human melanomas." (PMID 23912239, 2013). "This can be guided by the observations that most primary melanomas with a BRAF mutation have paired secondary lesions also harboring the mutation." (PMID 23951556, 2013). "BRAF: The standard-of-care mutation, exon 15 A/T aa600 was detected in both malignant melanoma clinical samples by the q-PCR method." (PMID 23922754, 2013). "It is interesting to note that in the majority of melanomas with mutations in BRAF or NRAS, the expression of c-KIT seems reduced to allow tumor progression." (PMID 24416617, 2013). "The most famous use of zebrafish in melanoma was to demonstrate the role of the BRAF V600E mutation in nevus formation, and to show that an additional mutation was needed to develop melanoma." (PMID 27429258, 2013). "Within the melanoma samples the BRAF expression levels varied between tumors harboring BRAF mutations and those wild-type for BRAF (p = 0.021)." (PMID 23673558, 2013). "Subsequently all phase II and III studies were conducted in selected melanoma patients with BRAF V600E mutation, which confirmed the phase I study findings and demonstrated improved response rate and overall survival in vemurafenib treated patients." (PMID 24252729, 2013). "Over 45 cancer-associated BRAF mutations have been identified with a high frequency in specific cancers, including 40–60% of melanoma, 30–50% of papillary thyroid, 5–20% of colorectal, and ∼30% of ovarian cancer." (PMID 23844038, 2013). "Nonetheless, a large number of missense mutations have been demonstrated as drivers, such as the BRAF V600E mutation in melanoma, and KRAS G12D and G12V mutations in colorectal cancer." (PMID 24205039, 2013). "Genetic classification of different melanoma subtypes has become very important, especially with the introduction of effective therapies targeting genetic alterations such as BRAF and KIT mutations." (PMID 23694694, 2013). "Considering the cases analyzed for mutations in both genes, we identified a BRAF or NRAS mutation in 339/528 (64%) melanoma lesions." (PMID 23987572, 2013). "Activating mutations in the BRAF gene have been reported in 40–70% of melanomas and activating mutations in the NRAS gene in another 10–30%." (PMID 23658559, 2013). "New medications like vemurafenib have been developed for the systemic therapy of advanced melanomas in subpopulations identified by BRAF mutation tests." (PMID 23738077, 2013).